ALK (ALK receptor tyrosine kinase)
Diseases named in the same sentence as ALK in open-access papers (continued):
Sharing a sentence is not in itself a finding about the gene and the disease.
cancer (continued). "Additional molecular mechanisms can affect ALK signaling in human cancer other than chromosomal translocations/inversions: ALK up-regulation/amplification and ALK gene mutations." (PMID 29495603, 2018). "sweyjawbu RNA expression is associated with ALK gene amplification or translocation status in a number of different types of cancer cells." (PMID 27974674, 2017). "Aside from translocations, other genetic alterations in the ALK gene that have been characterized in cancer pathogenesis include activating point mutations, amplifications of the ALK locus, alternative transcription, and small deletions." (PMID 28895885, 2017). "Some authors reported that ALK rearrangements were more common in patients with poorly differentiated adenocarcinoma whilst EGFR mutations were typical of well-differentiated cancers." (PMID 28938691, 2017). "The search for autophagy gene abnormalities (amplification, deletion, mutations) in ALK-associated cancers would also bring useful information on the status of autophagy in primary and/or relapsed ALK-associated tumors." (PMID 29186933, 2017). "Despite the preliminary successes reported for ALK kinase inhibition in ALK+ ALCL, it is worth noting that resistance mutations similar to those seen in other ALK+ cancers have been reported both in patients and in vitro." (PMID 29035291, 2017). "In this review, we will first briefly describe the autophagic process and how it can lead to opposite outcomes in anti-cancer therapies, and we will then focus on what is currently known regarding autophagy in ALK-associated cancers." (PMID 29186933, 2017). "Patients with EGFR mutations or ALK-fusions are recommended to receive targeted therapy of tyrosine kinase inhibitors (TKIs), which significantly prevents the progression of cancer and improves patients’ prognosis." (PMID 29285248, 2017). "For the purpose of this review, we will focus our discussion on the ALK-associated cancers for which autophagy has been found to be activated in response to therapy." (PMID 29186933, 2017). "A growing spectrum of cancers has been associated to the ALK oncogene, which has boosted the research towards ALK tyrosine kinase inhibition." (PMID 29186933, 2017). "Abnormal expression of fused ALK genes has been implicated in the pathogenesis of several types of cancer, including non-small-cell lung cancer (NSCLC), anaplastic large-cell lymphoma, glioblastoma, and neuroblastoma." (PMID 28245558, 2017). "In literature, autophagy has been shown to be induced upon therapies in different kinds of ALK-associated cancers." (PMID 29186933, 2017). "The expression of sweyjawbu RNA has been associated with ALK gene amplification or translocation in various cancers." (PMID 28032602, 2017). "As a successful result of such a mobilization, an arsenal of ALK tyrosine kinase inhibitors (ALK TKIs) is now available, and their use has been proven to be beneficial in many ALK-associated cancer patients." (PMID 29186933, 2017). "EMT phenotype is also thought to be associated with resistance to targeted therapy in EGFR-driven NSCLC and in ALK-rearranged NSCLC treated with ALK TKIs as well as in K-Ras mutated cancers." (PMID 27119231, 2016). "More mutations of ALK gene have been reported in several cancers, including NSCLC, inflammatory myofibroblastic tumors, diffuse large B cell lymphoma, colon cancer, renal cell carcinoma, breast carcinoma, esophageal cancer, and neuroblastoma." (PMID 26951079, 2016). "Most mutations of the ALK gene are in the form of a translocation with another partner gene leading to a fusion oncogene which becomes overtly expressed in cancers." (PMID 26951079, 2016). "We report here for the first time the identification of this mutation in any ALK-fusion cancer, in a cell line selected in crizotinib." (PMID 27009859, 2016).
cancer (continued). "These include novel variants with respect to ALK-fusion cancers, R1192P and T1151M, and with respect to ALCL, F1174L and I1171S." (PMID 27009859, 2016). "Molecular targeted therapies for specific genomic alterations, such as epidermal growth factor receptor (EGFR) mutations and anaplastic lymphoma kinase (ALK) gene rearrangements, are among the greatest innovations in the field of personalized cancer therapy." (PMID 27050074, 2016). "In conclusion, our study has provided novel insights into the mechanism underling the resistance to Crizotinib in ALK+ cancers." (PMID 27641368, 2016). "The gene that encodes a receptor protein called Anaplastic Lymphoma Kinase (or ALK for short) is often mutated in some types of human cancer so that the protein is always active." (PMID 26418745, 2015). "Crizotinib is the best known ALK tyrosine kinase inhibitor and is used to treat ALK-associated cancers." (PMID 26640600, 2015). "Nowadays, ALK small-molecule inhibitors are among the most promising agents in several high-risk cancers, based on the fact that ALK, when activated by mutation, amplification or gene rearrangement, becomes highly oncogenic." (PMID 26147305, 2015). "In the wide spectrum of ALK mutations, R1275Q and F1174L are the most frequently reported mutations in cancer that result in dysregulation of ALK activity and signalling." (PMID 25874976, 2015). "Crizotinib is the most advanced ALK tyrosine kinase inhibitor and is already used in clinics to treat ALK-associated cancers." (PMID 26338968, 2015). "Expression of CD44, a marker linked to the CSC phenotype in some cancers, was also undetectable in the H3122 cells both before and after ALK inhibition." (PMID 25238228, 2014). "Hypoxia is involved in the resistance to chemotherapeutic treatments in several cancers, and we investigated the association between the responses to ALK inhibitors and hypoxia." (PMID 25096400, 2014). "KIT amplification, auto-phosphorylation of EGFR, and aberrant expression of other receptor tyrosine kinases have also been postulated by in vitro experiments to cause resistance to crizotinib in ALK-rearranged cancer cells." (PMID 24279718, 2013). "Anaplastic lymphoma kinase (ALK) is a human gene that can also become an activating mutation found in several types of cancer." (PMID 25031935, 2012). "As with many kinase domain mutations implicated in cancer, the F1174 and R1275 mutations in ALK leads to phosphorylation of downstream targets and result in heightened cell proliferation, invasion, and survival." (PMID 22347506, 2012). "The ALK gene, which encodes a receptor tyrosine kinase, is implicated in various cancers and may promote tumorigenesis and progression through mutations or fusions." (PMID 40636700, 2025). "In general, these ALK variants are associated with multiple cancer types." (PMID 40606598, 2025). "ExoDx Lung (ALK) accurately identifies the EML4-ALK mutation in cancer cells by analyzing exosomal RNAs in the blood, while ExoDx Lung (T790M) detects the EGFR T790M mutation, and ExoDx Lung (EGFR) identifies both EGFR activation and T790M resistance mutations." (PMID 41573685, 2025). "Importantly, we demonstrated that lorlatinib retains efficacy against these mutations, suggesting its potential for therapeutic repurposing in other ALK-mutated cancers." (PMID 40606598, 2025). "We investigated whether SNPs of the 13 cancer-immunity relevant genes would associate with the anti-ALK antibody titer of a subset of patients (n = 80)." (PMID 41469691, 2025). "The rearrangement and overexpression of wild-type or mutated ALK may lead to aberrant ALK signaling and cause numerous cancers." (PMID 38804307, 2024). "Anaplastic Lymphoma Kinase (ALK) has been implicated in several human cancers." (PMID 38339401, 2024). "Moreover, NVP-TAE684 is a selective inhibitor of anaplastic lymphoma kinase (ALK), which is associated with the pathogenesis of various cancers and can serve as an important therapeutic target." (PMID 38506898, 2024).
cancer (continued). "However, these patients eventually relapse as their cancers inevitably develop resistance through secondary ALK mutations or activation of alternative bypass signaling pathways that drive oncogenic progression." (PMID 38458397, 2024). "Anaplastic Lymphoma Kinase (ALK) is a protein linked to cancer growth." (PMID 38339401, 2024). "Similarly, ATP‐binding site mutation (ALK‐G1269A) and near αC helix site mutations (ALK‐C1156Y, ALK‐L1152R, ALK‐F1174C, and ALK‐1151T insertion) were identified in ALK‐rearranged cancers, conferring resistance by causing conformational changes." (PMID 39184861, 2024). "Importantly, an increasing menu of highly CNS-active targeted therapies including for EGFR-variant and ALK-rearranged malignant neoplasms allows a growing proportion of patients to avoid metastasectomy and/or brain radiation." (PMID 37906192, 2023). "ALK amplification and mutations are also thought contribute to carcinogenesis in certain cancers." (PMID 36991452, 2023). "One plausible reason for suboptimal treatment response to crizotinib could be the higher prevalence of ALK mutations over fusions in this cancer cohort." (PMID 37773318, 2023). "Importantly, the combination of small eccDNAs originated from ETV6 (cut‐off point: 0.000019) and ALK (cut‐off point: 0.000022) showed great multi‐cancer diagnostic value in tissues." (PMID 37649244, 2023). "Indeed, ALK TKI have been employed in preclinical and clinical studies to assess the efficacy and safety of ALK inhibition in cancer cells harboring ALK point mutations." (PMID 36765519, 2023). "The high multi‐cancer diagnostic value of small eccDNAs originated from ALK&ETV6 could be extrapolated from tissues (AUC = 0.804) to plasma and showed high positive predictive value (100%) and negative predictive value (82.35%) in a validation cohort." (PMID 37649244, 2023). "In addition, more patients with stage III-IV cancer were found in the ALK mutation group (P < 0.001)." (PMID 36338735, 2022). "Coinciding with BRAF, ALK has been considered as a driving event in several cancer types due to its mutation and amplification, while the expression of ALK in AML samples and high-risk group is contrarily elevated, making it a risk factor to indicate oncogenesis and poor prognostic." (PMID 36292722, 2022). "In this study, we investigate whether P-gp overexpression can contribute to reduced susceptibility of cancer cells to the anaplastic lymphoma kinase (ALK) inhibitor ensartinib." (PMID 35565470, 2022). "Most of the time, the ALK gene remains dormant, but it could cause cancers by genetic rearrangement, gene fusion, or gene overexpression once it is activated." (PMID 35370632, 2022). "Further study using cancer cell lines with ALK mutations will reveal the involvement." (PMID 35701529, 2022). "ALK activation in cancer is caused by ALK fusion proteins as well as ALK overexpression." (PMID 35508387, 2022). "Whether the shift from epithelial to mesenchymal phenotypes should be viewed as an ALK mutation-independent, cancer cell-autonomous phenomenon that drives cross-resistance to new-generation ALK–TKIs is still under debate." (PMID 36551587, 2022). "Genomic aberrations in oncogenes such as epidermal growth factor receptor (EGFR) mutations and anaplastic lymphoma kinase (ALK) fusions have defined different molecular subtypes of NSCLC with unique cancer biology and response to matched tyrosine kinase inhibitors (TKI)." (PMID 35159091, 2022). "To investigate the relationship between BI-ALCL and cALCL and detect gene fusions, we applied an RNA sequencing (RNA-seq) approach, investigating 1385 genes recurrently translocated, mutated or deregulated in cancer, in 12 cALCLs, 10 BI-ALCLs and 2 ALK+ sALCLs." (PMID 34944796, 2021). "For instance, cfDNA could be analyzed with the aim of searching for specific mutations in EGFR/ALK genes, identifying driver mutations in a group of cancer patients, or broadly exploring and analyzing methylated cfDNA in BC patients." (PMID 33522650, 2021).
cancer (continued). "Aberrant ALK activity has been strongly implicated in the oncogenesis of human cancer as a fusion protein in inflammatory myofibroblastic tumors, diffuse large B-cell lymphoma and anaplastic large-cell lymphoma, or through mutations in the full-length protein in hereditary familial neuroblastoma." (PMID 33452442, 2021). "Recently, accumulating evidence has shown that acquired resistance to chemotherapeutic drugs such as platinum, epidermal growth factor receptor tyramine kinase (EGFR-TK) inhibitors, and anaplastic lymphoma kinase (ALK) inhibitors is associated with increased PD-L1 expression in cancer cells." (PMID 32024543, 2020). "In addition to functional approaches, a bioinformatics approach called Prediction of T Cell Epitopes for Cancer Therapy (ProTECT) has been recently developed to identify ALK neoepitopes from recurrent ALK R1275Q mutation." (PMID 32059449, 2020). "Anaplastic lymphoma kinase (ALK) is a receptor tyrosine kinase of the Class XVI that has been found to be implicated in multiple cancers through aberrant activation due to point mutations, overexpression, or a diversity of translocations giving rise to fusion proteins." (PMID 33287140, 2020). "In addition to ALK fusions, ALK point mutations are found in 26 cancer types with an average mutation rate of 1.5%." (PMID 32059449, 2020). "In addition to ALK-rearrangements, would other ALK aberrations e.g., mutations be able to alter the PD-L1 axis, thus rendering other ALK-altered cancers amendable to anti-PD-L1 therapy?" (PMID 32059449, 2020). "Regardless, because ALK fusion genes are associated with several types of cancer and these findings suggest a possible role for ALK in cGAS-STING signaling, the relationship between ALK-EGFR-AKT and components of the STING pathway ought to be thoroughly examined with further studies." (PMID 32774773, 2020). "A recent study has identified several missense mutations in ALK associated with cancer." (PMID 30726988, 2019). "Only the two ALK mutations were associated with a specific ID in the COSMIC cancer database." (PMID 31452835, 2019). "However, deregulation of ALK activity—including mutations, amplifications, and translocations—has been characterized in a subset of cancers." (PMID 30726988, 2019). "We also examined whether cancer stem cell-like (CSC) properties existed in such ALK-TKI-resistant cells, which are closely linked to EMT features." (PMID 29930762, 2018). "Several translocations, mutations or amplifications render ALK oncogenic in different cancer types." (PMID 30290811, 2018). "Notably ALK amplification, mutations and especially chromosomal rearrangements have been found in several cancers." (PMID 30134812, 2018). "This activation is controlled by ALK, which has been implicated in NB and other cancers." (PMID 29555900, 2018). "However, the characterization of ALK as a driver mutation in cancer pathogenesis has led to the introduction of targeted ALK therapies in the treatment of ALK-positive ALCL." (PMID 28895885, 2017). "ALK translocation has become a promising candidate for a therapeutic target as well as a diagnostic molecular marker described for NSCLC cancer patients due to the excellent responses observed in lung tumors with the ALK rearrangement treated with ALK inhibitors." (PMID 29312572, 2017). "This approach could help to decipher the importance of autophagy in ALK tumorigenesis, and also to develop new ways to improve ALK-associated cancer personalized therapies." (PMID 29186933, 2017). "For unknown reasons, the ALK locus appears to be a hotspot for translocations, with 22 different translocation partners identified and implicated in the pathogenesis of several cancer types." (PMID 28895885, 2017). "ALK is a receptor tyrosine kinase that, when altered by chromosomal inversion, translocation, amplification or mutation, plays an oncogenic role in certain cancers." (PMID 27844328, 2017).
cancer (continued). "Mutations or fusions of both EGFR and ALK may be primary causes of cancer, whereas both the EGFR gatekeeper mutant T190M and MET may generate drug resistance." (PMID 29086093, 2017). "However, a variety of alterations in the ALK gene such as mutations, overexpression, amplification, translocations, or other structural rearrangements have been implicated in human cancer tumorigenesis." (PMID 26802023, 2016). "ALK has also been described as rearranged or mutated in other cancer types and, in all the cases, its deregulated kinase activity leads to the activation of several downstream pathways such as MEK/ERK, STATs and AKT/mTOR, which result in abnormal proliferation and block of apoptosis." (PMID 27662658, 2016). "A similar strategy could be employed to target other types of cancer‐driving genomic changes, such as the rearranged anaplastic lymphoma kinase (ALK) allele and K‐ras mutations." (PMID 26747090, 2016). "In addition, ALK activation in cancer can also arise through overexpression and mutation of full-length ALK." (PMID 26338968, 2015). "Interestingly, we have also found that these Chinese male never-smoker patients in our study are strongly associated with younger-onset and less-differentiated carcinomas, which are likely caused by aberrant expression of ALK mRNA and protein." (PMID 25407901, 2014). "In addition, these findings suggested that a cancer cell line that harbors a concurrent ALK rearrangement and an EGFR mutation would be expected to be resistant to both single agent ALK and EGFR inhibitors." (PMID 23714228, 2013). "Though much regarding the function of LTK remains unknown, it shares a high degree of similarity with anaplastic lymphoma kinase (ALK), which is found mutated in human cancer." (PMID 22347506, 2012). "Finally, some ALK compound mutations, like L1198F + C1156Y confer resistance to lorlatinib through steric interference with the drug binding but paradoxically enhance binding to crizotinib and resensitize cancer cells to polder ALK inhibitors." (PMID 41228269, 2025). "Finally, among rare variants from the mother, as cancer driver genes, a missense mutant ALK (chr2: 30143039G > T, V163L, rs55697431), and a stop-gain mutant BRCA2 (chr13: 32911104C > A, S871Ter, rs397507634) were focused through screening using the IntOGen database." (PMID 34367235, 2021). "Thus, targeted therapy against both NLRR1 and ALK might be possible to treat patients with particular cancers such as high-risk NB." (PMID 27604320, 2016). "In addition, ALK was also mutated or amplified frequently in many cancers." (PMID 25193856, 2014). "Therapeutic interventions targeting epidermal growth factor receptor (EGFR) and anaplastic lymphoma kinase (ALK) have significantly improved the treatment of metastatic lung cancer by interfering with signaling pathways essential to cancer progression." (PMID 41596524, 2026). "Similar to HER2 or ALK/ROS1 testing in other cancers, this approach holds clinical promise for OSCC." (PMID 41463200, 2025). "While ALK mutations are typically associated with benign or low malignant potential in IMT, the mutation in this case is situated in a cancer hotspot region, suggesting a potential risk of malignant transformation." (PMID 40636700, 2025). "To date, 21 different genes have been identified as ALK fusion partners, each activating distinct signaling pathways that influence cancer cell proliferation, invasiveness, and tumorigenicity." (PMID 40852483, 2025). "This work validates ALK as an outstanding immunotherapy target across a spectrum of childhood and adult cancers and provides rationale for the clinical development of a first-in-class ALK-directed ADC." (PMID 40813394, 2025). "Cancers can develop resistance to treatment with ALK tyrosine kinase inhibitors (ALK‐TKIs) via emergence of a subpopulation of drug‐tolerant persister (DTP) cells that can survive initial drug treatment long enough to acquire genetic aberrations." (PMID 39369284, 2025).